PRSS3P1 (PRSS3 pseudogene 1)
Synonyms: TRY5
Gene: Unprocessed pseudogene on chromosome 7 (142,760,415 to 142,763,943, forward strand). Ensembl gene ENSG00000250591.
Diseases named in the same sentence as PRSS3P1 in open-access papers:
PRSS3P1 is named in the same sentence as 2 diseases in open-access papers, as found by Europe PMC text mining. Sharing a sentence is not in itself a finding about the gene and the disease.
PRSS3P1 shares sentences with these, for which no sentence is quoted: breast carcinoma (1 paper); cancer (1).